PCSK9 (proprotein convertase subtilisin/kexin type 9)
Diseases named in the same sentence as PCSK9 in open-access papers (continued):
Sharing a sentence is not in itself a finding about the gene and the disease.
coronary artery disease (continued). "In our study, in a group of Chinese Han T2DM patients, the plasma level of PCSK9 was positively correlated with the severity of coronary heart disease, as shown by the linear correlation results (diseased vessels: r = 0.35, p < 0.001; GS: r = 0.46, p < 0.001, significantly)." (PMID 38115042, 2023). "Obviously, this assoсiation may indicate the influence of genetically elevated PCSK9 on the development of coronary artery disease and T2DM simultaneously." (PMID 38028979, 2023). "Moreover, PCSK9 inhibitors suppress the accumulation of the proinflammatory cytokine IL-6 in the plasma of stable coronary artery disease patients with the IL6-74CC genotype and high level of lipoprotein(a)." (PMID 36970356, 2023). "Similarly, proprotein convertase subtilisin/kexin type 9 (PCSK9) inhibitors have shown efficacy in the treatment of coronary artery disease, and upregulation of PCSK9 has been identified in human CAVD and promotes VIC calcification in vitro." (PMID 35355968, 2022). "The plasma PCSK9 amounts were positively related to the white blood cell counts, indicating the presence of chronic low‐grade inflammation and its subset of lymphocytes in stable coronary artery disease patients." (PMID 36330745, 2022). "Consequently, circulating PCSK9 concentration has been proposed to be a novel biomarker for predicting major adverse cardiovascular events (MACEs) in coronary artery disease (CAD)." (PMID 35596184, 2022). "Finally, we established a causal patho-mechanistic network of GE and PE of IL6R, PCSK9, TFPI, and AXL and coronary artery disease providing possible new therapy targets." (PMID 35604899, 2022). "Therefore, to investigate the effects of PCSK9 inhibitors on CAC progression, we performed a calcium score analysis of the randomized control study comparing PCSK9 inhibitors vs. standard statin therapy in patients with coronary artery disease." (PMID 35600486, 2022). "Our data suggest that the PCSK9 (rs2149041) polymorphism is associated with an increased risk of increased CIMT in asymptomatic individuals without coronary artery disease determined by the absence of a CAC score." (PMID 36294964, 2022). "Our observation is consistent with the lack of excess T2D risk observed in PCSK9 inhibitor clinical trials and with strong protective effects for coronary heart disease." (PMID 36575460, 2022). "Furthermore, those who had PCSK9 dysfunctional mutations also had reduced LDL-c levels and an 88% decreased risk of coronary artery disease." (PMID 36005422, 2022). "The present study was specifically designed to explore the relationships between circulating levels of PCSK9, comprehensive circulating determinants of the atherosclerotic risk and precise characterization of coronary artery disease in contemporary patient populations with suspected CAD." (PMID 31672148, 2019). "Although lowering of LDL-C levels with PCSK9 inhibitors has been shown to reduce cardiovascular events in statin-treated patients with coronary artery disease and acute coronary syndrome, little information is available about other effects of long-term low LDL-C levels." (PMID 30657536, 2019).
coronary artery disease (continued). "The demonstration in 2004 that loss of function mutations in PCSK9 lower low-density lipoprotein levels and protect from coronary artery disease, and the successful cholesterol-lowering PCSK9 inhibitors consequently developed, have served as longstanding exemplars for many complex diseases." (PMID 30957210, 2019). "Therefore, PCSK9 is a prevailing lipid-lowering target to prevent coronary heart diseases and stroke." (PMID 27280970, 2016). "Several SNPS, such as rs11591147 in PCSK9, rs1260326 in GCKR, rs10455872 in LPA, rs964184 in ZPR1, rs58542926 in TM6SF2, and rs182611493 in MAU2 have been clinically associated with multiple metabolic disorders, including coronary heart disease, hyperlipidemia, non-alcoholic fatty liver disease." (PMID 41608459, 2026). "While PCSK9 gain-of-function (GOF) mutations associated with elevated blood lipids, carriers of loss of-function (LOF) mutations benefited from low-density lipoprotein cholesterol (LDL-C) reduction by up to 28%, accompanied by an 88% reduced risk of coronary artery disease." (PMID 38907775, 2025). "Therefore, they may be particularly useful for analyzing the impacts of age of therapeutics such as statins and/or PCSK9 inhibitors that target these pathways and in the context of coronary heart disease." (PMID 40403091, 2025). "In order to predict major adverse cardiovascular events (MACEs) in coronary artery disease (CAD), circulating PCSK9 levels were proposed as a new biomarker." (PMID 37765005, 2023). "In addition, PCSK9 levels are associated with a higher plasma concentration of fibrinogen (r = 0.211, p = 0.002) and C reactive protein (CRP) (r = 0.153, p = 0.023) in patients with coronary artery disease (CAD)." (PMID 35683632, 2022). "Although statins, ezetimibe, and PCSK9 inhibitors are the standard of care for coronary artery disease, many novel LDL cholesterol–lowering drugs, such as inclisiran recently approved by the FDA, may transform the care of patients who are at risk of life-threatening coronary events." (PMID 36687675, 2022). "Then, our lipid clinic is a hub for the management of HeFH and other severe hyperlipidaemias, so our cohort could be different compared to one of the cardiology units, managing more coronary heart disease patients, for whom PCSK9 inhibitors are more easily reimbursed." (PMID 36012937, 2022). "Moreover, the results of available epidemiological, preclinical, and clinical studies have indicated that plasma PCSK9 concentration is correlated with glycemic parameters and can predict the adverse cardiovascular events in diabetic patients with coronary artery disease." (PMID 33581713, 2021). "The relationships between circulating PCSK9 levels, coronary disease and risk, is complex and might be partially independent of LDL cholesterol." (PMID 31672148, 2019). "Most notably, the discovery of missense and loss-of-function variants in PCSK9 that lower LDL cholesterol and protect against coronary artery disease suggested that inhibition of PCSK9 may be a useful therapeutic strategy for prevention and treatment of cardiovascular disease." (PMID 29691411, 2018). "Studies had investigated the associations between proprotein convertase subtilisin/kexin type 9 (PCSK9) E670G polymorphism and coronary artery disease (CAD) and lipid levels, but the results were controversial." (PMID 26576960, 2015). "In African Americans, loss-of-function mutations in PCSK9 that prevent its secretion are associated with a 30%–40% reduction in plasma levels of LDL-C, but surprisingly reduce events associated with coronary atherosclerosis (CAD, coronary artery disease) by 88% over a 15 year period." (PMID 25180781, 2014).
coronary artery disease (continued). "The selected genetic instruments were validated by analyzing the correlations between drug-related SNPs and the coronary heart disease as the positive control (Pvalues for HMGCR and PCSK9 were 3.291E-05 and 2.000E-10, respectively)." (PMID 37746259, 2023). "However, this is at odds with the results of the study involving stable coronary heart disease patients who were naïve to lipid-lowering therapy, they reported a positive correlation between PCSK9 and WBC, which might be due to the difference existing in the study population." (PMID 37904138, 2023). "With excellent efficacy and safety profiles, 2 monoclonal antibodies against PCSK9 have been developed to lower elevated LDL-c levels and subsequently help prevent coronary heart disease (CHD)." (PMID 36595504, 2023). "As PCSK9 inhibitors have been demonstrated to significantly and safely reduce LDL-C, discussions have begun to explore its optimal timing in coronary artery disease, especially in subjects with acute coronary syndrome (ACS)." (PMID 37200976, 2023). "Proprotein convertase subtilisin/kexin type 9 (PCSK9), a marker of local vascular inflammation in coronary artery disease, and classical inflammatory markers procalcitonin (PCT) and high‐sensitivity C‐reactive protein (hsCRP) were also studied." (PMID 36053856, 2023). "We analyzed the short-term effects of one-time administration of evolocumab (PCSK9 inhibitor) on the lipid profiles (especially Lp(a)) and inflammatory markers in Korean patients with coronary artery disease (CAD) who underwent percutaneous coronary intervention (PCI)." (PMID 35448076, 2022). "Platelets store and release PCSK9 upon activation, which is enhanced in the presence of LDL cholesterol, not only ex vivo but also in patients with coronary artery disease." (PMID 35806908, 2022). "Pcsk9 is related to incidence and prognosis of coronary artery disease (CAD) and with lipid or non-lipid cardiovascular risk factors." (PMID 34044829, 2021). "Thus, our data establish pltPCSK9 as a relevant factor for atherothrombosis and thrombo-inflammation, which might at least partially be relevant for the highly efficient effects of PCSK9 inhibitors to reduce mortality and other adverse cardiovascular events in coronary artery disease." (PMID 34681838, 2021). "In a large cohort of patients with coronary artery disease (CAD), platelet count, platelet reactivity, and platelet-derived PCSK9 release were analyzed." (PMID 34681838, 2021). "Intentional disrupting PCSK9 activity by loss of function mutations, therapeutic PCSK9 protein antibodies, or siRNA mediated gene silencing, could significantly reduce circulating LDL-C levels, inhibit cardiomyocytes autophagy, and lower the risk of coronary heart disease." (PMID 34805315, 2021). "Key questions that remain to be addressed are how PCSK9-lipoprotein interactions differ in plasma during the fasted and postprandial state as well as in patients with hyperlipidemia and coronary artery disease (CAD)." (PMID 34601896, 2021). "Inhibition of PCSK9 results in lowered plasma LDL and improves prognosis in patients with coronary artery disease." (PMID 34681838, 2021). "Here, we show that PCSK9 and CETP, two genes whose inactivation is thought to protect humans against coronary artery disease, are lost in many independent mammalian lineages." (PMID 33575564, 2020). "Genetic variation in proprotein convertase subtilisin/kexin type 9 (PCSK9) gene has been recently identified as an important determinant of plasma LDL-cholesterol and severity of coronary heart disease." (PMID 17940607, 2007). "This study aimed to address the lack of data on PCSK9, coronary heart disease (CHD) severity, and major cardiovascular events (MACEs) in patients with type 2 diabetes mellitus (T2DM)." (PMID 38115042, 2023).
coronary artery disease (continued). "Consistent reductions in LDL-C levels were observed across all subgroups at week 12 and were not mediated by sex, ezetimibe use, baseline PCSK9 levels, statin intensity or presence of coronary artery disease." (PMID 36855099, 2023). "We examined whether specifically statins, of the major lipid modifiers (statins, proprotein convertase subtilisin/kexin type 9 (PCSK9) inhibitors and ezetimibe) have pleiotropic effects on ischemic heart disease (IHD) via testosterone in men or women." (PMID 32838838, 2020). "The incidence of coronary artery disease, heart failure, and peripheral artery disease was higher in tertile 3 PCSK9, but it was not statistically significant." (PMID 31963408, 2020). "Serum PCSK9 levels positively correlated with white blood cell count (WBCC), a traditional and easy-to-measure marker of chronic low grade inflammation, in patients with stable coronary artery disease." (PMID 29343301, 2018). "Non-sense mutations resulting in loss-of-function of PCSK9 are associated with significant reduction of both LDL-C levels and coronary heart disease risk, with no adverse clinical consequences." (PMID 30761308, 2018). "Among non-diabetic individuals with angiographically-defined coronary artery disease who are not taking a lipid-lowering medication, plasma PCSK9 levels are elevated at the time of acute myocardial infarction." (PMID 25180781, 2014). "This is a well-established phenomenon, e.g., truncation mutations in PCSK9 that are of low frequency in African Americans and absent in individuals of European origin, that result in a robust reduction in LDL-C levels and coronary heart disease risk." (PMID 23236364, 2012). "PCSK9 therapies for coronary heart diseases are also likely not to be hampered by potential central nervous system effects." (PMID 24278757, 2012). "Recent clinical trials demonstrated that proprotein convertase subtilisin/kexin 9 (PCSK9) inhibitors reduce cardiovascular events without affecting systemic inflammation in the patients with coronary artery disease, as determined by high sensitivity C-reactive protein (CRP) levels." (PMID 39149582, 2024). "In addition, PCSK9 inhibitors did not change high sensitivity C-reactive protein (CRP) levels in the patients with coronary artery disease." (PMID 39149582, 2024). "This has important clinical implications because it suggests that allocation of add-on therapies to lower lipid levels, such as proprotein convertase subtilisin/kexin type 9 inhibitors, in patients with high LDL-C levels could be informed by severity of coronary artery disease." (PMID 35147685, 2022). "The study showed administration of the PCSK9 inhibitors to statin-treated patients with coronary artery disease produced significantly lower rate of CAC progression, and the results might be partially related to the Lp(a) lowering effects with PCSK9 inhibitors." (PMID 35600486, 2022). "So, here we focused on ischemic heart disease (IHD), using the UK Biobank to investigate whether testosterone mediated any of the effects of statins, PCSK9 inhibitors or ezetimibe on IHD in men or women using univariable and multivariable MR." (PMID 32838838, 2020). "This is a well-established phenomenon; for example, truncation mutations in PCSK9 that are of low frequency in African Americans, but absent in European Americans, have been shown to result in a robust reduction in LDL-C levels and coronary heart disease risk." (PMID 22629316, 2012). "No data is currently available regarding the relation of PCSK9 to cardiovascular metabolic markers (CVMMs) and major adverse cardiovascular events (MACEs) in stable coronary artery disease (CAD) patients with diabetes or without diabetes." (PMID 33023603, 2020). "Therefore, the aim of this study was to investigate correlations between serum levels of PCSK9 and apoB-containing atherogenic lipoproteins such as Lp(a); small, dense LDL; and oxidized LDL in patients with coronary artery disease (CAD)." (PMID 27658826, 2016).
coronary artery disease (continued). "However, the original finding implicating PCSK9 and LDL cholesterol came not from GWAS, but from sequencing in families with autosomal dominant high LDL levels and an increased incidence of coronary heart disease." (PMID 23696745, 2013).